BRAF (B-Raf proto-oncogene, serine/threonine kinase)
Diseases named in the same sentence as BRAF in open-access papers (continued):
Sharing a sentence is not in itself a finding about the gene and the disease.
melanoma (continued). "TNFR2 expression has been reported on melanoma cell lines, however, the prevalence and function of TNFR2 on melanomas (BRAF-mutated in particular) is poorly understood." (PMID 35879777, 2022). "For this kind of tumor, recently the FDA also approved the combination of encorafenib (a BRAF inhibitor) and binimetinib (a MEK inhibitor), and this combination is able to improve PFS and OS in patients with BRAF-mutated melanoma." (PMID 35628540, 2022). "Acquired BRAF inhibitor resistance presents a significant clinical challenge as there are only few effective treatment options for melanomas that have developed secondary BRAF-inhibitor resistance." (PMID 36358868, 2022). "MAPK/ERK phosphorylates and inhibits LKB1, which is an upstream activator of AMPK and thereby blocks the activation of AMPK in BRAF (V600E)-driven melanoma." (PMID 36297833, 2022). "During the recruitment period, new treatment options emerged for metastatic disease and melanoma survival increased with therapies such as immune-checkpoint inhibitors or BRAF inhibitors for patients with BRAF-positive melanomas." (PMID 35626014, 2022). "A number of papers have correlated the oncogenic BRAF function with the promotion of pro-survival autophagy and consequent melanoma cell survival and propagation." (PMID 36009541, 2022). "The development of targeted inhibitors against MEK and BRAF represented a milestone in melanoma therapy, but patients eventually relapse due to acquired resistance mechanisms." (PMID 35267510, 2022). "Currently, limited data is available on targeted therapy and immunotherapy sequencing in patients with B-Raf Proto-Oncogene (BRAF)-mutant melanoma." (PMID 35456332, 2022). "In patients with BRAF-mutated melanoma, MEK inhibitors are more frequently used in association with BRAF inhibitors to definitely block ERK activity and the associated cell proliferation." (PMID 35163058, 2022). "Combining cIAP1/2 inhibitor with BRAF/MEK inhibitors delays the onset of acquired resistance in melanomas in vivo." (PMID 35296667, 2022). "Combined inhibition of MEK and BRAF V600E turned out as a successful strategy for melanoma patients and in addition, reduce the cutaneous adverse events of developing cSCCs very efficiently." (PMID 35174094, 2022). "For example, a mainstay of therapy for advanced melanoma is combination therapy with BRAF/MEK inhibitors, but resistance develops rapidly to this combination." (PMID 36538362, 2022). "These are BRAF-driven melanoma that has been previously characterized to stochastically switch between round/ameboid/contractile shapes and spindle/mesenchymal/protrusive forms when embedded, or cultured on the surfaces of collagen hydrogels." (PMID 36039362, 2022). "Expression of ERK1 and ERK2 proteins, which are mutant for these ubiquitination sites, results in decreased ERK activation and renders melanoma cells resistant to the BRAF inhibitor PLX4032 (vemurafenib)." (PMID 35884430, 2022). "After early suggestions that non-BRAF-driven melanomas exhibit different sensitivities to immunotherapy, subsequent studies concluded that all genetic subtypes similarly respond to immune checkpoint blockade." (PMID 35234863, 2022). "Here the authors show that activation of Hippo signalling by oncogenic BRAF represents an additional safeguard to limit BRAF-dependent human melanocyte growth and melanoma formation." (PMID 35768444, 2022). "In melanoma, MUC16 alterations have been frequently found to be associated with BRAF V600E mutations and higher TMB than wild-type patients." (PMID 35884534, 2022). "In BRAF-mutant (V600E) melanoma cells, the Myc transcription factor and Myc-activated glutamine metabolism are essential for resistance to BRAF inhibitors." (PMID 35011702, 2022). "Accordingly, a pilot study in patients demonstrated that treating BRAF inhibitor-resistant melanoma patients with HDAC inhibitors killed the drug-resistant cell population." (PMID 35814399, 2022).
melanoma (continued). "Here we critically review the evidence supporting ERK5 as a mediator of BRAFi/MEKi and ERK1/2i resistance, both in BRAF-mutant melanoma and in RAS-driven tumours." (PMID 35903549, 2022). "Melanoma can arise from BRAF-V600E melanocytic nevi, suggesting mechanisms of senescence escape at play." (PMID 35306485, 2022). "AHF assigned each panel member a question on BRAF testing for early diagnosis and treatment of melanoma and CRC in LA." (PMID 36589179, 2022). "Encorafenib (LGX818, trade name Braftovi), a novel BRAF inhibitor, has been approved for the treatment of melanoma and colorectal cancer." (PMID 36559089, 2022). "BRAF-targeted kinase inhibitors (KIs) are used to treat malignancies including BRAF-mutant non–small cell lung cancer, colorectal cancer, anaplastic thyroid cancer, and, most prominently, melanoma." (PMID 35486732, 2022). "In this study, RT-PCR was utilized to detect BRAF AV in 103 plasma samples from AJCC stage I–IV melanoma patients, including 48 AJCC stage IV patients who received BC." (PMID 35205608, 2022). "Although patients with BRAF-mutant melanoma with BM had fair local control on BRAF plus MEK inhibitors, the competing risk of death and distant intracranial and extracranial progression was high." (PMID 36579260, 2022). "For example, a phase I clinical trial (NCT01400451) aimed to test the combination of vemurafenib with ipilimumab in patients with metastatic BRAF-mutant melanoma, had to be terminated due to the high incidence of hepatotoxicity." (PMID 36358912, 2022). "One of the last frontiers for melanoma therapy is the triple therapy strategy, consisting of BRAF inhibitors + MEK inhibitors + immune checkpoint inhibitors." (PMID 35160279, 2022). "Similar to Kdm4d inhibitors, bromodomain and extraterminal motif (BET) inhibitors, when combined with BRAF/MEK inhibitors, can also efficiently kill melanoma cell lines mutated for BRAF." (PMID 36551603, 2022). "Using a panel of human, immunocompetent genetically engineered mouse, and patient-derived tumor models, dab-SiR penetration was assessed across BRAF-mutant tumors of melanoma, anaplastic thyroid cancer, ovarian cancer, and mCRC." (PMID 35486732, 2022). "Even when this mutation is present, drug response to BRAF inhibitors is heterogenous with some melanomas more resistant to BRAF inhibition (BRAFi) than others." (PMID 35581546, 2022). "However, we found a statistical interaction between PD-L1+ PMN frequency and BRAF status (p=0.01), suggesting that the predictive significance of PD-L1+ PMN frequencies could be modified in the different settings of this parameter (BRAF mutated vs. wild-type melanoma) across the study cohort." (PMID 36016960, 2022). "As BRAF mutations are more common in melanoma, studies utilizing CRISPR/Cas9 for chemotherapeutic agents have often revolved around the melanoma." (PMID 35620280, 2022). "For a second melanoma patient treatment was adjusted by BRAF-directed (dabrafenib-trametinib) adjuvant treatment." (PMID 35053600, 2022). "The selection of new NRAS mutations is the principal cause of melanoma reactivation in BRAF- or NRAS-mutant cases, explaining why BRAF-mutant or NRAS-mutant melanomas exhibit the largest resistance to B-Raf inhibitors." (PMID 36143375, 2022). "The addition of an anti- RAS, RAF, MEK, ERK agent, MEK inhibition (MEKi) has shown considerable effects and ability to inhibit growth and induce melanoma cell death, especially in the BRAF-mutant metastatic melanoma." (PMID 35334544, 2022). "We also demonstrate that functional impairment of the Hippo pathway enables oncogenic BRAF-expressing melanocytes to bypass nevus formation and rapidly form melanomas." (PMID 35768444, 2022). "Peiffer and colleagues indicated that BRAF/MEK inhibitors can promote the proliferation of melanoma-specific T cells in patients with melanoma." (PMID 36077696, 2022).
melanoma (continued). "Two years later, based on the results of the Phase III trial (NCT01227889), another targeted agent against BRAF mutations, Dabrafenib (GSK21188436), was also approved by the FDA for the treatment of advanced melanoma." (PMID 35912223, 2022). "The mechanisms of melanocyte senescence have been extensively explored in the context of melanoma, particularly BRAF V600E OIS within naevi (moles)." (PMID 36551868, 2022). "BRAF mutations are believed to arise from UV damage, though they appear to be more common in skin intermittently exposed to the sun rather than chronically exposed and may also be more common in melanomas in younger patients, lending credence to the Intermittent Exposure Hypothesis." (PMID 35712493, 2022). "Combined PD-1, BRAF and MEK inhibition significantly prolonged the survival time of patients with advanced BRAF-mutant melanoma." (PMID 35487914, 2022). "The analyzed data suggested that the combination of the BRAF inhibitor encorafenib and the MEK inhibitor trametinib demonstrated the highest anti-tumor activity in both, BRAF- and NRAS-mutated melanoma." (PMID 36230853, 2022). "In a retrospective analysis of 28 acral and 12 patients with mucosal BRAF-mutant melanoma treated with BRAF inhibitors, objective response rate (ORR) of BRAF inhibitors were 38.1% and 20%, respectively." (PMID 35640549, 2022). "The first evidence of dabrafenib activity in BRAF V600E NSCLC was reported in one patient who achieved a response in a phase 1 trial mainly enrolling BRAF-mutant melanoma patients." (PMID 36230797, 2022). "In fact, CDK2 has been identified as a key driver of melanoma resistance against BRAF and Hsp90 inhibitors." (PMID 36230567, 2022). "One of the most common mechanisms of vemurafenib resistance in malignant melanoma is AS of BRAF, occurring in 15–30% of patients." (PMID 35883549, 2022). "The BRAF-V600E mutation in the B-raf proto-oncogene (BRAF gene) (7q34), which is detected in 80–90% of HCL cases, is also identified in various solid tumors such as melanoma." (PMID 35205796, 2022). "Case Summary: A 55-year-old Chinese female was diagnosed with BRAF wild-type oral malignant melanoma by excisional biopsy and genetic test." (PMID 35979233, 2022). "In contrast, activating NRASQ61K mutations have mainly been reported as arising in the context of BRAF inhibitor resistance in melanoma." (PMID 35689207, 2022). "Three of these lncRNAs-IGF2AS, MEG3, ZEB2-AS1—were identified as independent prognostic factors in BRAF-mutant advanced melanoma patient sera treated with vemurafenib." (PMID 35159386, 2022). "Later on, SEMA6A deregulation in BRAFV600E as compared with BRAF wt melanoma patients has been reported by others." (PMID 35440004, 2022). "MAPK signaling, tumor metabolism and resistance to BRAF inhibitors are suggested to be interconnected in melanoma." (PMID 35327519, 2022). "Two BRAF inhibitors (BRAFi) targeting the BRAFV600E mutation were approved in Europe and United States for the treatment of patients with advanced melanoma (stages III and IV): vemurafenib and dabrafenib." (PMID 36286442, 2022). "For example, one study described upregulated expression of the collagenase and metalloproteinase MT1-MMP in melanoma cells, which acquired resistance to the BRAF inhibitor Vemurafenib." (PMID 36119516, 2022). "Our evaluation of the TCGA model using an external BRAF-mutant melanoma dataset resulted in clinically relevant predictions based on tumor RNA-seq samples from the patients." (PMID 36167836, 2022). "Our ultimate goal is to determine the alteration(s) responsible for the aggressive behavior of melanoma cells with a combined resistance to a BRAF and a MEK inhibitor that is presently favored in the clinic." (PMID 36551563, 2022). "Melanomas often have mutations in BRAF and RAS, and investigators have explored the use of BRAF/MEK inhibitors to treat melanoma in preclinical and clinical studies." (PMID 36221123, 2022).
melanoma (continued). "We thus examined the clustering and spatial distribution of phosphorylated DDR in melanoma cells plated on collagen I‐coated plastic dishes or on 3D ECMs, in response to oncogenic BRAF pathway inhibition." (PMID 34957688, 2022). "In the present study, we observed that SEMA6A expression is higher in BRAF-mut than in BRAF-wt melanoma patients and has a prognostic significance in BRAF-mut patients from TCGA and DFCI large cohorts." (PMID 35440004, 2022). "BRAF V600E -positivity was less frequent in Spitzoid melanomas compared to the other melanoma types (35.1% vs. 68.4%), while all five tumours positive for ALK were Spitzoid melanomas." (PMID 35037531, 2022). "A retrospective analysis of encorafenib plus binimetinib also reported intracranial activity in patients with BRAF-mutant melanoma brain metastases, including patients previously treated with targeted therapy." (PMID 35538491, 2022). "Similar dose-limiting toxicities were found with the pan-PI3K inhibitor BKM120 and the BRAF inhibitor vemurafenib in BRAFV600-mutant advanced melanoma patients (NCT01512251)." (PMID 35806358, 2022). "Another example is reported from an analysis of the evaluation of the combination BRAF and MEK inhibitor (dabrafenib/trametinib) for stage III melanoma with BRAF600 mutation positive." (PMID 36134249, 2022). "In preclinical models of melanoma, intermittent dosing with BRAF inhibitors results in delayed emergence of resistance as compared to continuous dosing." (PMID 35814399, 2022). "Recent study has shown that RSK inhibitors BI-D1870 and BRD7389 significantly reduced the proliferation of BRAF mutant melanoma cells that have acquired resistance to dual BRAF and MEK inhibitor treatment." (PMID 36210843, 2022). "One of these studies pointed out that primary melanoma cell lines with BRAF mutation are more sensitive to SMO inhibitor, sonidegib, than BRAF wild-type cells." (PMID 36139698, 2022). "This suggests that CCND1 amplification is mutually exclusive with BRAF, RAS, and NF1 mutations, which account for the three most common mutant genes observed in melanoma." (PMID 35844619, 2022). "According to our results, those patients who harbored BRAF wild-type AM showed a survival benefit when compared to patients with BRAF V600-mutant melanomas." (PMID 35885042, 2022). "Our in vitro results were strongly supported by data obtained from a cohort of BRAF-mut melanoma patients admitted to dabrafenib+trametinib treatment." (PMID 35440004, 2022). "Treatment of melanoma with a BRAF inhibitor (BRAFi) frequently initiates development of BRAFi resistance, leading to increased tumor progression and metastasis." (PMID 36551563, 2022). "Recently, a study identified that melanoma cells insensitive to BRAF inhibitors are characterized by a remarkable expression of the metalloproteinase MT1-MMP and other components of ECM, such as fibronectin and collagen." (PMID 36551603, 2022). "Although chloroquine also suppressed the proliferation of BRAF‐mutant melanoma cells in a dose‐dependent manner, its IC50 values in Sk‐Mel‐5, Sk‐Mel‐28 and A375 cells were 16, 19 and 7 μM respectively." (PMID 35332658, 2022). "Patients were ‘pre-screened’ with clinically available MassARRAY® BRAF test, Colon Panel, Melanoma Panel, or ThyroSPECTM." (PMID 34981751, 2022). "In BRAF-mutated melanoma, the inhibition of PDE4 activity by pharmacological inhibitors or RNA interference decreases melanoma cell invasion by interacting with the focal adhesion kinase FAK." (PMID 35158973, 2022). "More recently, SAMMSON has been shown to be important for human melanoma cell growth and survival while also highlighting the role of a SAMMSON in modulating the adaptive resistance of mutant BRAF melanoma to RAF inhibitors." (PMID 36139698, 2022). "Targeting vemurafenib-resistant cells in melanoma is of great interest, as, despite the clinical efficacy of selective BRAF inhibitors such as vemurafenib, resistance to treatment often develops." (PMID 35624662, 2022).
melanoma (continued). "Melanoma patients who were resistant to the BRAF inhibitor showed higher levels of autophagy through the endoplasmic reticulum stress response." (PMID 35992821, 2022). "Studies using a murine melanoma model have shown that tumorigenesis is closely related to the kinase-dead BRAF (D594A) and oncogenic RAS." (PMID 35163468, 2022). "Inhibition of BRAF in BRAF-mutant melanoma cells reverses these processes and can restore tumor–immune recognition." (PMID 36500607, 2022). "BRAF mutants are present in >50% of melanoma patients as well as in colorectal (5−10%), thyroid carcinomas (25−45%), hairy cell leukemia (∼100%) and less commonly in ovarian and lung malignancies." (PMID 36500607, 2022). "CCK‐8 and colony formation assays indicated that lj‐2‐66 significantly inhibited the proliferation of BRAF‐mutant melanoma cells." (PMID 35332658, 2022). "This happens because it has been shown that 15–20% of primary melanomas can become resistant to drugs, such as BRAF/MEK inhibitors." (PMID 36289813, 2022). "Congruently, the subgroup analysis restricted to BRAF wild type melanoma patients showed that PD-L1+ PMN frequency emerges as an independent predictive factor in this patient subgroup selectively." (PMID 36016960, 2022). "Although activation of these molecules within the RAS pathway leads to the activation of ERK1/2, BRAF- and NRAS-mutated melanomas represent two different clinical and biochemical entities, as they exhibit different signaling patterns and biological responses." (PMID 36402789, 2022). "Vemurafenib (BRAF inhibitor)-resistant melanoma cell lines showed increased phospho-AKT levels, while the addition of either AKT or mTORC1 inhibitors led to the reversal of resistance." (PMID 35806358, 2022). "Overall, our data indicate for the first time that ITF2357 targets oncogenic BRAF in melanoma cells and induces a switch from autophagy to classic apoptosis, thus representing a possible candidate in melanoma targeted therapy." (PMID 36009541, 2022). "This study assessed risk factors and the results of treatment with anti-PD-1 antibodies, anti-CTLA4 antibodies and BRAF/MEK inhibitors for advanced malignant melanoma." (PMID 35406444, 2022). "In this retrospective study, we analyzed serum samples from 70 BRAF-mutant melanoma patients coming from two cancer centers namely the National Cancer Institute IRCCS "G." (PMID 36438490, 2022). "Having previously shown that the combination of HSV oncolytic virotherapy and BRAFi is effective in BRAF mutant thyroid cancer, we wished to test this approach in the clinically more common setting for use of these drugs, namely melanoma." (PMID 35338089, 2022). "In BRAF WT melanomas, miR-205 was found to significantly explain only distant metastasis-free survival (p-value = 0.046)." (PMID 35326682, 2022). "So far, Binimetinib in combination with encorafenib (BRAF inhibitor) is approved in several countries for the treatment of advanced BRAF-mutant melanoma." (PMID 35965686, 2022). "In parallel, other studies highlighted that ddPCR should be the primary method for detecting and monitoring BRAF V600E-mutant melanomas." (PMID 35887633, 2022). "The combinations of LXH254 and trametinib or the ERK inhibitor, LTT462, are currently in evaluation in patients with previously treated BRAF V600 or NRAS mutant melanoma (NCT04417621)." (PMID 35053435, 2022). "For BRAFV600-mutant melanoma, treatment with BRAF and MEK inhibitors has resulted in high objective response rates, but most responses are short-lived." (PMID 36428582, 2022). "In the presence of drug, BRAF-mutant melanoma cells appear to suppress DUSP4 expression to compensate for the acute loss of oncogenic signals." (PMID 35580987, 2022). "The purpose of the present study is to dissect the role of SEMA6A in the biology of BRAF-mut melanoma, and to explore its predictive potential towards dual BRAF/MEK inhibition." (PMID 35440004, 2022).